IL6 (interleukin 6)
Diseases named in the same sentence as IL6 in open-access papers (continued):
Sharing a sentence is not in itself a finding about the gene and the disease.
respiratory failure (continued). "Among the IL-6 inhibitors, tocilizumab is the most widely used therapeutic option in patients with SARS-CoV-2-associated severe respiratory failure (SRF)." (PMID 36012968, 2022). "As an important mediator of CRS, IL-6 appears to be correlated to respiratory failure, acute respiratory distress syndrome, and adverse clinical outcomes." (PMID 35242747, 2022). "Severe pulmonary involvement and higher levels of CRP, IL-6, D-dimer, AST, creatinine, myoglobin, and lower levels of Tlymp, Hb, and 25(OH)D were associated with respiratory failure." (PMID 35172759, 2022). "For patients requiring mechanical ventilation for acute respiratory failure, the results of IL-6 test strip also exhibited a high correlation with ELISA results, R2 = 0.974." (PMID 35242747, 2022). "The recent COVID-19 pandemic is also associated with respiratory failure from ARDS and is the leading cause of mortality, accompanied by hyperinflammation, increased level of IL-1β and IL-6 in these patients." (PMID 33806560, 2021). "Consistent with this, IL-6 is a potent pro-inflammatory cytokine, and serum IL-6 levels predict respiratory failure." (PMID 33730024, 2021). "Third, higher levels of IL-6, IL-8, IL-10, and TNF-α at admission were associated with respiratory failure and disease deterioration." (PMID 34088317, 2021). "Levels of D-dimers, activated partial thromboplastin time (aPTT), C-reactive protein (CRP), and interleukin (IL)-6 were significantly higher in patients with severe compared with moderate respiratory failure." (PMID 34638691, 2021). "IL-6 also induces the recruitment and stimulation of fibroblasts in the alveoli and the successive deposition of the extracellular matrix, which leads to respiratory failure and lung fibrosis." (PMID 34452063, 2021). "CRP and IL-6 concentrations were significantly higher in the blood of patients with severe respiratory failure compared to patients with moderate respiratory failure, while in this group the highest values were found at acute onset." (PMID 34638691, 2021). "The rapidly progressive nature of respiratory failure corresponds with a cytokine storm, including IL1β, IL6, IL8, TNFα, detected in broncho-alveolar lavage fluids." (PMID 33362557, 2020). "On this basis, IL6 inhibitors are currently being tested in China and Italy in patients with respiratory failure, and other IL6 inhibitors are also being considered." (PMID 32574270, 2020). "One study found that the immune dysregulation in patients with severe respiratory failure was due to a significantly increased production of IL-6 and defective lymphoid function because of an IL-6-mediated decrease in HLA-DR expression on CD14 monocytes." (PMID 32808850, 2020). "In the majority of patients (4/5) IL-6 levels were markedly elevated (>80 ng/ml) during the disease course, a finding shown to predict respiratory failure and mechanical ventilation, previously." (PMID 32922409, 2020). "Elevated serum IL‐6 levels predict imminent respiratory failure and correlate with acute respiratory distress syndrome in COVID‐19 patients." (PMID 32838038, 2020). "Elevated IL-6 levels were detected in hospitalized patients and have been associated with ICU admission, respiratory failure, and poor prognosis in several studies." (PMID 33019628, 2020). "Pre-operative IL-6 levels were significantly increased in patients who developed respiratory failure (P < 0.001)." (PMID 22040874, 2011). "Furthermore, IL-6 and TNF-α have been associated with the onset of symptoms, length of hospital stay, respiratory failure and organ damage in many reports." (PMID 39528988, 2024). "In this pilot clinical observational study, using the IL-6 rapid diagnosis system, we performed two successive examinations of serum IL-6 concentrations after ED presentation to predict respiratory failure which required invasive or non-invasive ventilation support in elderly patients with CAP." (PMID 37214473, 2023).
respiratory failure (continued). "Among patients who did not receive IL-6 inhibitors, males were at increased risk of progression to respiratory failure or death compared to females (HR = 1.13; CI (0.72–1.79))." (PMID 37598275, 2023). "Significant pro-inflammatory properties are exhibited by IL-6, which plays an important role in cytokine storm syndrome, as elevated serum IL-6 levels correlate with respiratory failure and ARDS, which are mediated by two major signaling pathways: cis and trans." (PMID 37504277, 2023). "Therefore, this study aims to assess the efficacy of the IL-6 rapid diagnosis system for the early identification of elderly patients with CAP who are prone to developing respiratory failure in the emergency department (ED) of a hospital in Taiwan." (PMID 37214473, 2023). "Laboratory values that can help diagnose these conditions are high levels of neutrophils, C-reactive protein (CRP), troponin, myoglobin, d-dimer, lactate dehydrogenase (LDH), and IL-6; these parameters and low lymphocyte counts predict progression to respiratory failure and death." (PMID 35172759, 2022). "Moreover, CD33 and circulating IL-6 levels were higher among patients with severe respiratory failure, i.e., PaO2/FiO2 ratio of <13.3 kPa." (PMID 35625671, 2022). "ARDS, which was by far the main cause of respiratory failure in the study population, is characterized by persistent elevation in local and systemic levels of cytokines (namely IL-1β, TNF-α, IL-6, and IL-8), which contribute to the progression of lung injury and to extrapulmonary organ dysfunction." (PMID 35995816, 2022). "It remains unclear if 6 mg of dexamethasoneis enough in severe respiratory failure and if there could be a unique benefit oftargeted IL-6 blockade over steroids." (PMID 34180274, 2022). "First, transplant patients with severe COVID-19 disease (characterized by either death or prolonged course with respiratory failure requiring intubation) had the same elevated inflammatory markers (IL-6, CRP, ESR, fibrinogen, D-dimer, ferritin, and LDH) observed in non-transplant patients." (PMID 36591281, 2022). "In one study, Interleukin 6 (IL-6) biomarker levels greater than 80 picogram/milliliter (pg/mL), C-reactive protein level > 97 milligram/milliliter (mg/mL), IL-1beta > 0.064 pg/mL, and TNF-alpha > 2.23 pg/mL predict a greater risk of respiratory failure." (PMID 34356205, 2021). "IL-6 is likely a crucial mediator of respiratory failure, shock, and multiorgan dysfunction." (PMID 34682421, 2021). "The IL-6 levels increase according to the disease stage and correlate with respiratory failure." (PMID 33679753, 2021). "However, there is controversy if excessive IL-6 synthesis is true a cornerstone of the pathogenesis of respiratory failure in Covid-19 or is just an epiphenomenon of increased IL-1β and TNFα in the cytokine storm." (PMID 33781216, 2021). "However, if IL-6 levels remain elevated, chronic autoimmune diseases and inflammatory diseases such as respiratory failure can develop, as seen with SARS patients." (PMID 34452063, 2021). "Similar to IL-6 levels being a predictive factor in respiratory failure, LIF levels may indicate the severity of the infection in patients." (PMID 32595353, 2020). "Interleukins like IL6, IL8 and IL2 along with TNFα might be main causative inflammatory leading respiratory failure." (PMID 32617527, 2020). "Previous studies have shown that the immunological profile of critically ill COVID‐19 patients demonstrated hyperactivation of the humoral immune pathway, including interleukin‐6 (IL‐6), which is a critical mediator for respiratory failure, shock, and multiorgan dysfunction." (PMID 32838038, 2020). "Moreover, elevated IL-6 is correlated with respiratory failure, and high concentrations of IL-6 in the serum is considered one of the hallmarks of severe MERS-CoV infections." (PMID 32991323, 2020).
respiratory failure (continued). "Levels of IL-6 at first assessment might predict respiratory failure, other publications with longitudinal analyses demonstrated that IL-6 increases fairly late during the disease’s course, consequently compromising its prognostic value at earlier stages." (PMID 33019628, 2020). "Levels of IL-6 found to have potential to predict respiratory failure in patients." (PMID 32595353, 2020). "Indeed, several studies have shown higher than normal IL-6 levels in COVID-19 patients requiring hospitalization or presenting with acute respiratory failure." (PMID 33382773, 2020). "Using IL-6 or NF-κB inhibitors could be a useful strategy for decreasing mechanical ventilation-induced lung injury in respiratory failure patients." (PMID 23822633, 2013). "Moreover, following the development of AKI, increases in the levels of inflammatory cytokines, such as IL-6, also depend on its reduced renal clearance and may contribute to respiratory failure via kidney–lung crosstalk." (PMID 40005354, 2025). "Thus, IL-6 acts as a critical mediator of respiratory failure and multi-organ dysfunction." (PMID 39354444, 2024). "Hence, we propose the use of a point-of-care IL-6 rapid diagnostic system, which has a non-inferior performance to the ELISA test, as a tool for facilitating early detection of patients at risk of respiratory failure or disease deterioration." (PMID 37214473, 2023). "Additionally, immunological and biochemical variables such as the total number of neutrophils and lymphocytes, interleukin-6 (IL-6), C reactive protein (CRP), lactate dehydrogenase, d-dimers or ferritin levels have been associated with respiratory failure and death." (PMID 35547738, 2022). "We indicate cytokine hemoadsorption in patients with severe acute respiratory failure refractory or poorly responsive to prone positioning in the context of a hyperinflammatory state (determined by very high levels of biomarkers, such as IL-6, ferritin, and D-dimer)." (PMID 37386575, 2022). "The integration of a rapid, easy-to-use IL-6 test strip and a sensitivity-enhanced spectrometric reader makes this POC diagnostic device a promising tool for early recognition of patients who may develop respiratory failure requiring mechanical ventilation." (PMID 35242747, 2022). "In addition, IL-6 and MCP-1 have also been proposed as candidate markers for disease prediction in hospitalized patients with respiratory failure, and in the regression analysis we found IL-6 and MCP-1 in hospitalized patients to be the main predictors of death." (PMID 34539631, 2021). "Significant positive correlations were observed between inflammatory markers (CRP, IL-6) and both ICU admission and mechanical ventilation, underscoring the role of systemic inflammation in driving severe respiratory failure and critical care needs." (PMID 39857695, 2025). "At the same time, a minority of patients progress to a hyperinflammatory “cytokine storm” state with striking elevations of interleukin-6 (IL-6), C-reactive protein (CRP), ferritin, and D-dimer, which strongly correlate with respiratory failure and death." (PMID 41517263, 2025). "Excessive cytokine release, including IL-6, TNF-α, IFNα, INFβ, and INFγ, induces inflammation in the respiratory tract, resulting in airway closure, respiratory failure, and ultimately death." (PMID 39381111, 2024). "IL-1ra, IL-6, IL-8, MCP-1, MIP-3α, MIP-3β, and fractalkine were investigated regarding respiratory failure leading to mechanical ventilation during admission." (PMID 38985797, 2024). "PRRSV infection induces the expression and release of a large number of inflammatory factors (such as IL-1β, IL-6, IL-8, TNF-α, etc.), leading to acute inflammation in the lungs, ultimately leading to respiratory failure and death." (PMID 36552462, 2022). "IL-6 and its downstream target CRP reflect cytokine storm in the critical stage, thus, serving as useful indicators of respiratory failure and inferior prognosis." (PMID 36438922, 2022).
respiratory failure (continued). "Of note, the 6-mRNA score was significantly more accurate for predicting severe respiratory failure and death than the only assay under the FDA Emergency Use Authorization, the IL-6." (PMID 35042868, 2022). "Our study revealed the high correlation coefficients of the serum level of IL-6 and CRP to minimum SpO2/FiO2 ratio, demonstrating that increase of the two markers indicates respiratory failure within three days after laboratory measurement." (PMID 34441262, 2021). "According to known evidence, IL-6 is superior to CRP and other markers of inflammation in predicting respiratory failure in Covid-19." (PMID 33781216, 2021). "Additionally, the maximal IL-6 level (cutoff = 80 pg/mL) predicted respiratory failure with high accuracy (p = 1.7 × 10−8, AUC = 0.98), and patients with IL-6 levels higher than 80 pg/mL had 22 times higher odds of respiratory failure than those with normal IL-6 levels." (PMID 37287491, 2021). "Analysis of inflammatory markers and liver and kidney function tests in different groups of children with MPP revealed that those with respiratory failure had significantly elevated levels of white blood cells, neutrophil ratio, PCT, ESR, CRP, IL-6, IL-10, IFN-γ, ALT, AST, and LDH." (PMID 39849991, 2025). "Elevated levels of IL-6, particularly in the lungs (100 pg/mL), correlate with severe ARDS, emphasizing the need for early intervention with therapies targeting IL-6 or neutrophil infiltration to prevent further endothelial damage and respiratory failure." (PMID 39594987, 2024). "Santa Cruz and colleagues established IL-6 as a biomarker for developing Fatal Severe Acute Respiratory Syndrome Coronavirus 2 (SARS-CoV-2) pneumonia due to its positive correlation with C-reactive protein (CRP) and respiratory failure." (PMID 39192275, 2024). "Moreover, a study demonstrated that IL-6 and CRP in combination can predict the development of respiratory failure with substantial sensitivity and specificity." (PMID 35806986, 2022). "Inflammatory markers (LDH, CRP, CPK, IL-6) were 2–20 times higher among patients with respiratory failure compared to patients without respiratory failure (p < 0.05)." (PMID 36105073, 2022). "Inflammatory markers like IL-6 and CPK were > 15 times elevated in the respiratory failure group." (PMID 36105073, 2022). "In fact, we found that IL-6 levels were significantly higher in patients in stage IIb who will evolve to stage III, as compared to patients in stage IIb who will recover from their respiratory failure and enter stage IIa (p = 0.0022)." (PMID 33679753, 2021). "The results of a recent meta-analysis also showed that patients with complicated forms of COVID-19 (i.e. ICU admission and/or acute respiratory failure) had nearly three-fold higher serum IL-6 levels than those with non-complicated disease." (PMID 33382773, 2020). "Patients were not eligible if they exhibited respiratory failure requiring invasive mechanical ventilation, septic shock, or multiple organ dysfunction at enrollment or received cytokine inhibitory therapy (targeting IL-6, IL-6R, IL-1, or Janus kinase)." (PMID 37606044, 2023). "Also, a significant negative correlation was detected between IL-6 and IL-8 levels and SpO2, PaO2, which indicate respiratory failure." (PMID 37222789, 2023). "The novelty of our study lies in our approach of monitoring the sequential change of interleukin-6 (IL-6) concentrations, rather than solely relying on threshold values, to predict adverse clinical outcomes such as respiratory failure in patients upon their arrival to the emergency department." (PMID 37214473, 2023). "In stages characterized by hypoxemia (IIb and III), IL-6 levels did correlate with patient's respiratory failure severity, as we observed a significant negative correlation with SpO2 (r = −0.324, p = 0.0075) and a significant negative correlation with PaO2 (r = −0.335, p = 0.0026)." (PMID 33679753, 2021).
respiratory failure (continued). "Although we could not detect increased specific production of IL-6 in PBMC stimulated with peptide pools due to high background production in controls, we detected a dominant IL-6 and TNF-α response in cell culture supernatants from the patient deceased due to respiratory failure (case 3)." (PMID 32591408, 2020). "Thus, we postulate that in the absence of suPAR and IL6 levels, a simplified SCOPE could be used as an estimator of the risk of progression to severe respiratory failure and serve as a guide for the early use of anakinra." (PMID 36961847, 2023). "Also, we found a significant negative correlation between IL-6 levels during stages IIb and III, peripheral oxygen saturation (SpO2), and partial pressure of oxygen in arterial blood (PaO2), showing that IL-6 correlates with respiratory failure." (PMID 33679753, 2021).